MTOR (mechanistic target of rapamycin kinase)
Diseases named in the same sentence as MTOR in open-access papers (continued):
Sharing a sentence is not in itself a finding about the gene and the disease.
cervical carcinoma (continued). "Genistein also sensitized HeLa cervical cancer cell line to cisplatin, while preventing the increase in p-mTOR, p-AKT, and p-S6K1 generated by cisplatin treatment." (PMID 33918290, 2021). "To summarize, knockdown of ADGRG1 decreases tumorigenesis via blockade of the P13K/Akt/mTOR axis in cervical cancer." (PMID 34367958, 2021). "It is worth noting that BCAT1/Leu/mTOR/Autophagy is a concise mechanism for the cisplatin sensitivity of cervical cancer and HCC cells." (PMID 33568627, 2021). "A recent study indicated that FAM83A is regulated by miR-206 to promote cervical cancer development via the PI3K/AKT/mTOR pathway." (PMID 34659522, 2021). "In cervical cancer, CD38 has been linked to increased proliferation, inhibition of apoptosis and PI3K/AKT/mTOR signaling activation." (PMID 34830895, 2021). "In another study, icariin displayed the inhibition effect on the growth of human cervical cancer cells by targeting the mTOR/PI3K/AKT signaling pathway." (PMID 33777154, 2021). "In cervical tumors, FX was reported to have cytotoxic activity in the human cervical cancer cell line HeLa through suppression of the Akt/mechanistic target of rapamycin (mTOR) pathway and the subsequent autophagy induction." (PMID 34677429, 2021). "Meanwhile, EGCG enhances the sensitivity of cisplatin to cervical cancer cells by inhibiting the mTOR signaling pathway and the levels of p-p70S6K1 and p-4E-BP1, which in turn inhibits cell viability and induces apoptosis in HeLa cells." (PMID 34680171, 2021). "bergenin has been reported to have anticancer effects in cervical cancer and bladder cancer and to have a relationship with the mTOR pathway." (PMID 34194607, 2021). "In conclusion, isoflurane enhances proliferation of cervical cancer cells mediated by the activation of HDAC6 via mTOR pathway." (PMID 32833118, 2021). "Low-dose naltrexone inhibited PI3K/AKT/mTOR pathway and thus suppressed the proliferation of cervical cancer cells." (PMID 34339395, 2021). "Whole-exome sequencing of cervical carcinoma results confirmed that the ERBB2/PIK3CA/AKT/mTOR pathway was one of the major mechanisms of cervical cancer in tumorigenesis." (PMID 35070983, 2021). "ARCSP induced high expression of p-AMPK, p-raptor, LC3B-II, atg7, and p62 and low expression of p-mTOR and p-p70s6k in cervical cancer cells." (PMID 32962728, 2020). "We found that IRF-1 over-expression remarkably suppressed the expression of PI3K/mTOR signalling pathway-related proteins in cervical cancer cells." (PMID 33076322, 2020). "Akt immediately attained its activated state by phosphorylation (p-Akt) and activated Akt and mTOR are indicators of poor prognosis in cervical cancer patients." (PMID 32631421, 2020). "Former studies have delineated that AKT/mTOR pathway and Wnt/β-catenin pathway are key pattern regulating cancer progression, including in cervical cancer." (PMID 31682716, 2020). "A study investigating mTOR signaling of cervical cancer cell lines revealed high mTOR activity in CC." (PMID 31947591, 2020). "Activation of phosphatidylinositol 3-kinase (PI3K)/AKT/mammalian target of rapamycin (mTOR) pathway sometimes occurs in cervical cancer." (PMID 32961781, 2020). "Although several components differentially expressed in patients with ovarian, endometrial, and cervical cancer of the mTOR were identified, there are only a few investigated downstream actors in gynecological cancer connecting them with YB-1." (PMID 31947591, 2020). "In cervical cancer, Astrin can differentially regulate the mammalian target of rapamycin (mTOR) pathway in the process of tumor cell resistance to chemotherapeutic drugs including taxol." (PMID 32984344, 2020). "In conclusion, we revealed that down-regulation of GHET1 suppresses cervical cancer progression through regulating AKT/mTOR and Wnt/β-catenin signaling pathways, indicating GHET1 as a promising molecular biomarker for CC treatment improvement." (PMID 31682716, 2020).
cervical carcinoma (continued). "In cervical cancer, propofol suppressed cell viability and induced apoptosis by inhibiting of the mammalian target of rapamycin (mTOR)/p70 ribosomal protein S6 kinase (p70S6K) pathway." (PMID 32596964, 2020). "Mutations in PIK3CA are amongst the most frequently detected mutations in cervical cancer, but other alterations that result in the aberrant PI3K/AKT/mTOR activation, for instance genomic amplifications of PIK3CA or the loss of PTEN, are also reported." (PMID 31058807, 2019). "Cervical cancer patients are already subjects of (or included in) clinical trials testing PI3K/AKT/mTOR pathway inhibitors (e.g., NCT01958112, NCT01217177, NCT01026792, NCT01226316)." (PMID 31058807, 2019). "The mammalian target of rapamycin (mTOR) is one such signaling molecule that has been reported to be activated in cervical cancer." (PMID 31387554, 2019). "Inhibiting mTOR is cytotoxic to cervical cancer cells and creates a synergistic anti-tumor effect with conventional chemotherapy agents." (PMID 31387554, 2019). "In this study, we reveal that a natural compound rosmarinic acid methyl ester (RAME) exerts anti-cancer effects against cervical cancer by inhibiting mTOR/S6K1 pathway." (PMID 31387554, 2019). "These alterations in the PI3K/AKT/mTOR pathway can be considered ideal targets for the development of suitable drug targets in cervical cancer treatment." (PMID 29434241, 2018). "All of these results suggested that BMX promotes the proliferation of cervical cancer cells by activating the PI3K/AKT/mTOR and STAT3 pathways." (PMID 28514765, 2017). "Our study suggests that R7 is a promising chemotherapeutic agent for the treatment of cervical cancer and other PI3K/PTEN/Akt/mTOR signaling-associated tumors." (PMID 29312623, 2017). "Activation of mammalian target of rapamycin (mTOR) signaling has been demonstrated in aggressive cancers such as gastric and cervical cancer." (PMID 29214525, 2017). "Our data demonstrated that Zey induced substantial apoptosis of cervical carcinoma cells coincided with a corresponding reduction of cellular proliferation, which was associated with simultaneous inhibition of PI3K/AKT/mTOR and MAPK/ERK pathways." (PMID 28490807, 2017). "Studies exploring the activation of PI3K/AKT/mTOR signaling in HPV-induced cancers find that erlotinib can induce growth delay of xenografted HPV-containing cervical carcinoma cells." (PMID 28792525, 2017). "A similar inhibitory effect of PI3K/mTOR inhibitors on FDG uptake was already described in cervical cancer cells and confirms the well-known importance of the PI3K pathway for enhanced glucose metabolism." (PMID 28724379, 2017). "It thus will be interesting to determine how mTOR signaling is maintained in normoxic cervical cancer cell lines when the endogenous E6/E7 expression is silenced." (PMID 28678198, 2017). "Pretreatment with inhibitor of MEK/Erk, U0126, partially attenuated PGRN-stimulated mTOR phosphorylation in H8 cells, which was also confirmed in cervical cancer HeLa cells." (PMID 27517315, 2016). "DNA synthesis was enhanced in PGRN-treated HeLa cells, as compared with PBS-treated cervical cancer cells; likewise, DNA synthesis was decreased when mTOR signaling was inhibited by rapamycin in cells." (PMID 27517315, 2016). "Western blot assay showed that the protein level of PGRN and phosphorylation of mTOR at Ser2448 were increased in cervical cancer tissues compared with normal cervical tissues." (PMID 27517315, 2016). "The growth-promoting role of PGRN in tumors from mice with HeLa-cell implantation was inhibited with rapamycin treatment, so mTOR signaling was required for PGRN-stimulated progression of cervical cancer." (PMID 27517315, 2016). "rhPGRN-treated cervical cancer SiHa and HeLa cells also showed increased phosphorylation of mTOR at Ser2448." (PMID 27517315, 2016).
cervical carcinoma (continued). "Our study identified four cell metabolism associated proteins, mTOR, HIF-1α, c-Myc, and PKM2, as potential biomarkers to predict the response to cisplatin in cervical cancer patients." (PMID 27492148, 2016). "Based on these studies, we propose that metformin exerts its antitumorigenic effects and abolished TGF-β1-induced EMT through mTOR/p70s6k/PKM2 signaling in cervical carcinoma cells." (PMID 27916907, 2016). "Our findings reveal an essential pathological function of PGRN in regulating the mTOR signaling pathway in tumorigenesis of cervical cancer." (PMID 27517315, 2016). "We found that the mTOR/HIF-1α/c-Myc/PKM2 signaling pathway was significantly downregulated in post-chemotherapy cervical cancer tissues." (PMID 27492148, 2016). "Upon rapamycin treatment, we observed inhibition of mTOR signaling in both cervical cancer cell lines as evident from reduced phosphorylation of S6K upon rapamycin treatment." (PMID 27492148, 2016). "PKM2 enhances chemosensitivity to cisplatin through interaction with the mTOR pathway in cervical cancer." (PMID 27492148, 2016). "We infer that metformin is involved in mTOR/p70s6k/PKM2 signaling to promote cervical carcinoma resistance." (PMID 27916907, 2016). "Paclitaxel is found to activate the mTOR pathway in cervical cancer cell lines and its inhibition sensitizes the cells to treatment." (PMID 27090655, 2016). "High levels of mTOR, HIF-1α, c-Myc, and PKM2 were associated with a positive chemotherapy response in cervical cancer patients treated with cisplatin-based NACT." (PMID 27492148, 2016). "Here we identified a strong linkage between PGRN and phosphorylated-mTOR in cervical cancer tissues." (PMID 27517315, 2016). "Therapy targeting PI3K/Akt/mTOR signaling has shown meaningful clinical benefits in cervical cancer." (PMID 27517315, 2016). "The present study showed that PGRN contributed to the malignancy of cervical cancer, and inhibition of mTOR signaling by rapamycin disturbed PGRN-driven cervical cell transformation, proliferation and survival in vitro and tumor formation and growth in vivo." (PMID 27517315, 2016). "Based on the confirmation of PGRN binding to TNFR1 and TNFR2 in HeLa cells, we demonstrated that TNFR2 was needed for PGRN-stimulated mTOR signaling in cervical cancer cells." (PMID 27517315, 2016). "To investigate the biological consequence of PGRN-stimulated mTOR signaling in tumorigenesis of cervical cancer, we used nude mouse xenografts." (PMID 27517315, 2016). "Importantly, the staining intensity scores of PGRN and phosphorylated mTOR at Ser2448 in cervical cancer, CSC and CAC, were positively correlated, which suggests that cancer-associated activation of mTOR signaling may be involved in PGRN stimulation during the progression of cervical cancer." (PMID 27517315, 2016). "Pre-chemotherapy cervical cancer tissues consistently showed moderate or intense positive staining of mTOR, HIF-1α, c-Myc, and PKM2, while post-chemotherapy tissue consistently showed weak or moderate positive staining." (PMID 27492148, 2016). "Our result suggested that metformin inhibits TGF-β1-induced EMT via the mTOR/p70s6k/PKM2 signaling pathway in cervical carcinoma cells." (PMID 27916907, 2016). "Previous studies showed that SPAG5 overexpression can predict poor prognosis in lung cancer and cervical cancer and alter sensitivity to taxol treatment via the mTOR signaling pathway in cervical cancer." (PMID 27037000, 2016). "In this study, we first report that PGRN levels were positively correlated with level of phosphorylated-mTOR in cervical cancer." (PMID 27517315, 2016). "A tissue microarray analysis has shown that 13 cervical cancer patients (52%) express phosphorylated mTOR (p-mTOR) in the cytoplasm and membrane of cancer cells." (PMID 26022660, 2015). "The enzyme phosphatidylinositol 3-kinase (PI3K) is known to be overexpressed in cervical cancer, leading to phosphorylation of Akt and activation of mTOR signalling." (PMID 26264004, 2015).
cervical carcinoma (continued). "A high level of p-mTOR can serve as an independent prognostic marker to predict poor response to chemotherapy and survival of cervical cancer patients." (PMID 26022660, 2015). "Fourth, the results showed that LicA induced its effects on autophagy and apoptosis in cervical cancer cells via inhibition of the PI3K/Akt/mTOR signaling pathway." (PMID 26311737, 2015). "The expression of miR-99a and miR-125b-2 is downregulated in cervical cancer, causing TRIB2, HOXA1, and mTOR overexpression probably by the combination of both miRNAs’ loss." (PMID 26057746, 2015). "Our previous study and others have documented that the activated PI3K/AKT/mTOR pathway is frequently identified in patients with metastatic or recurrent cervical cancers." (PMID 25426553, 2014). "In general, SPAG5 upregulation relates to poor prognosis in cervical cancer patients, and SPAG5 is a regulator of mTOR activity during taxol treatment in cervical cancer." (PMID 24853425, 2014). "All these results suggest that cervical cancer cell lines have activated mTOR pathway under basal conditions and wide variations existed in p-AKT levels." (PMID 24705275, 2014). "Further, NAC attenuated AMPK activation under starvation condition and enhanced mTOR signaling in cervical cancer cell." (PMID 25028602, 2014). "Under SPAG5 downregulation, the sensitivity of cervical cancer cells differed according to taxol dose, which correlated with mammalian target of rapamycin (mTOR) signaling pathway activity." (PMID 24853425, 2014). "The present study described AZD8055 as a potent mTOR inhibitor involved in multiple cellular responses, including inhibiting proliferation and inducing apoptosis in human cervical cancer HeLa cells." (PMID 23420667, 2013). "Our detection of frequent PI3K/AKT/mTOR pathway alterations in HPV+ tumors is consistent with a recent report demonstrating PI3K pathway activation and sensitivity to mTOR inhibition in both cervical carcinoma and HPV+ HNSCC." (PMID 23718828, 2013). "To investigate the molecular mechanism of AZD8055 on HeLa cells, we examined the effect of AZD8055 on the activity of mTOR, an important component of the PI3K/Akt/mTOR signaling pathway that plays a crucial role in the pathogenesis of cervical cancer." (PMID 23420667, 2013). "In the present study, the high expression of the mTOR pathway in pathological cervical tissues was observed, as well as in cervical cancer cell line." (PMID 23443110, 2012). "Recent studies have shown that aberrant activation of mTOR is involved in many cancers and the activation status of the mTOR pathway in cervical cancer has been investigated." (PMID 23443110, 2012). "Combining PI3K/AKT/mTOR inhibitors with standard chemotherapy not only reduces chemotherapy resistance but has also demonstrated significant sensitization effects in preclinical studies on cervical cancer and liver cancer." (PMID 40725100, 2025). "In this study, we aimed to determine whether the effects of RACK1 on the proliferation and apoptosis of cervical cancer cells depend on fatty acid synthesis mediated by the AKT/mTOR/SREBP1 signaling pathway." (PMID 39425259, 2025). "The effects of isoflurane on cervical cancer have been completely different, which may be related to the different mTOR upstream signaling molecules affected by isoflurane." (PMID 40309242, 2025). "Furthermore, the role of FOXK2 in regulating lipid metabolism reprogramming in cervical cancer and its effects on the mTOR/DRP1 axis were validated in xenograft tumor models." (PMID 40641601, 2025). "Importantly, in GJB5-silenced cervical cancer cells, the restoration of Akt-mTOR activation through the expression of caAkt1 reversed the inhibitory effects on cell proliferation and migration." (PMID 40537499, 2025).
cervical carcinoma (continued). "PIWIL2 overexpression in cervical cancer initiates metabolic reprogramming via PDK1 upregulation, causing a shift in cellular metabolism from oxidative phosphorylation to glycolysis and the sequential activation of PI3K/AKT/mTOR signaling." (PMID 39849644, 2025). "The effects of silibinin on the mTOR pathway in cervical cancer cells have also been explored." (PMID 39836338, 2025). "It has been proven that ECT2 also promotes cervical cancer progression by regulating the AKT/mTOR pathway, and the expression levels of p-AKT and p-mTOR are also significantly increased in cells overexpressing ECT2, while the opposite is true for underexpressing ECT2." (PMID 40655948, 2025). "A study demonstrated the potential of cardamom treatment for attenuating cell proliferation in mTOR inhibitor-resistant HeLa cervical cancer cells by reducing the phosphorylation of mTOR and S6K1, indicating a promising avenue for further research and development." (PMID 39334932, 2024). "Furthermore, TRIM21 promoted autophagosome formation and reduced cell proliferation by inhibiting NCAPH expression and the downstream AKT/mTOR pathway in cervical cancer cells." (PMID 39103348, 2024). "Research findings have unveiled that impaired lysosomal activity and inhibition of autophagy synergistically contribute to the cytotoxic demise of cervical cancer cells induced by autophagy-linked anticancer peptides, operating through the AMPK/mTOR signaling axis." (PMID 38460947, 2024). "Little is known about the relationship between mTOR and ROS in cervical cancer, but recent studies suggest that HPV oncoproteins may be involved in the activation of the PI3K/Akt/mTOR pathway, potentially promoting tumorigenesis." (PMID 39629272, 2024). "Furthermore, TRIM21 inhibited cell proliferation by hindering NCAPH-mediated activation of the AKT/mTOR pathway and autophagosome formation in cervical cancer." (PMID 39103348, 2024). "The AKT/mTOR pathway plays an important role in the regulation of cervical cancer cell growth." (PMID 39103348, 2024). "Considering limited therapeutic options in recurrent cervical cancer, further validation of combined mTOR and ER inhibition in selected patients could appear promising." (PMID 37623437, 2023). "Thus, SLC5A3 mediates cervical cancer cell growth, at least partially, by promoting Akt-mTOR activation." (PMID 37324953, 2023). "In conclusion, the present study identified 14 EMT-related genes and 30 genes involved in the PI3K/AKT/mTOR pathway in cervical cancer, and they might provide novel clues for future treatment." (PMID 36911370, 2023). "Silencing SLC3A2 inhibits mTOR pathway activity and cell proliferation in cervical cancer cells." (PMID 37940982, 2023). "It is speculated that ADAMTS12 may regulate the invasion and migration of cervical cancer cells by affecting the mTOR signaling pathway." (PMID 37642715, 2023). "Furthermore, SLC5A3 knockdown or KO downregulated myo-inositol levels, induced oxidative injury, and decreased Akt-mTOR activation in cervical cancer cells." (PMID 37324953, 2023). "As it has a key role in the control of HPV gene expression and development of cervical cancer, the PI3K/AKT/mammalian target of rapamycin (mTOR) pathway may have potential as a therapeutic target for cervical cancer." (PMID 36911370, 2023).